SYF2 (SYF2 pre-mRNA splicing factor)
Description:
Involved in pre-mRNA splicing as component of the spliceosome.
Synonyms: CBPIN; p29; DKFZp564O2082; NTC31; fSAP29
Tractability: Small molecule: a structure with a bound ligand is known. PROTAC: UniProt records ubiquitination sites on it; ubiquitination databases record sites on it; its protein half-life has been measured.
Gene: Protein-coding gene on chromosome 1 (25,222,276 to 25,232,504, reverse strand). Ensembl gene ENSG00000117614.
Subcellular location: Nucleus
Subcellular location (Human Protein Atlas): Nuclear speckles
Pathways (Reactome):
Metabolism of RNA: mRNA Splicing - Major Pathway
Gene Ontology:
Molecular function: protein binding; RNA binding
Biological process: mRNA splicing, via spliceosome; positive regulation of cell population proliferation
Cellular component: catalytic step 2 spliceosome; nuclear speck; nucleus; post-mRNA release spliceosomal complex; post-spliceosomal complex; spliceosomal complex; U2-type catalytic step 1 spliceosome; U2-type catalytic step 2 spliceosome; nucleoplasm; Prp19 complex
Genetic constraint (gnomAD): Loss-of-function variants: 18 observed, 30.39 expected, observed/expected ratio (o/e) 0.59, 90% interval 0.41 to 0.88. The upper end of that interval is the gene's LOEUF score, 0.88, which puts it in group 3 of 6, group 1 being the genes least tolerant of losing a copy. Missense variants: 267 observed, 304.35 expected, observed/expected ratio (o/e) 0.88, 90% interval 0.79 to 0.97. Synonymous variants: 109 observed, 108.9 expected, observed/expected ratio (o/e) 1, 90% interval 0.86 to 1.17.
Homologues: Orthologues: chimpanzee SYF2 (99% identical), macaque SYF2 (97% identical), rabbit SYF2 (95% identical), guinea pig SYF2 (93% identical), pig SYF2 (92% identical), mouse Syf2 (91% identical), rat Syf2 (91% identical), tropical clawed frog syf2 (80% identical), zebrafish syf2 (77% identical), Drosophila melanogaster CG12343 (52% identical), Caenorhabditis elegans syf-2 (46% identical).
Diseases named in the same sentence as SYF2 in open-access papers:
SYF2 is named in the same sentence as 23 diseases in open-access papers, as found by Europe PMC text mining. Sharing a sentence is not in itself a finding about the gene and the disease. The quoted sentences say what the papers report.
breast carcinoma (5 papers, 2017 to 2022). "Then, Kaplan–Meier survival analysis showed that high expression of SYF2 had a significant association with poor prognosis after surgical resection in all breast cancer patients." (PMID 29179448, 2017). "In fact, high protein levels of SYF2 were associated with bad prognosis in breast cancer, and we found that ZRANB2 mRNA levels were up-regulated 5.4 fold (P < 0.002) in a published dataset of non-responding versus responding breast tumors analyzed before chemotherapy using eprirubicin." (PMID 31943118, 2020). "SYF2 participates in the progress of diverse tumor entities, such as breast cancer, gastric cancer (GC), human epithelial ovarian cancer (EOC), hepatocellular carcinoma, esophageal squamous cell carcinoma (ESCC), and glioma, in a cell cycle-dependent pathway." (PMID 36118875, 2022). "The expression pattern of DE mRNA according to the tumor stage in mRNAs was downregulated in breast cancer tissue, SYF2 and DTWD1 showed a more down-expressed pattern as the cancer progressed." (PMID 36294892, 2022). "For example, overexpression of SYF2 affects the cell cycle or cell proliferation leading to the occurrence and progress of breast cancer, non-small cell lung cancer, and ovarian cancer." (PMID 36118875, 2022). "In order to verify the role of SYF2 in breast cancer, we performed a series of experiments and found that SYF2 expression was upregulated in BC specimens and BC cell lines." (PMID 29179448, 2017). "Future prospective studies in a larger patient population are necessary to evaluate the prognostic value of SYF2 in breast cancer." (PMID 29179448, 2017). "We also confirmed the positive correlation of SYF2 expression with Cyclin D1 and cell proliferation of breast cancer cells." (PMID 29179448, 2017). "In the present study, we demonstrate the potential role of SYF2 expression in breast cancer progression." (PMID 29179448, 2017). "Firstly, our study revealed that SYF2 was overexpressed in breast cancer tissues and breast cancer cells in both Western blot and immunohistochemistry analysis." (PMID 29179448, 2017). "In summary, we confirmed that SYF2 was upregulated in breast cancer tissues and cells, and there was a positive correlation between SYF2 expression and proliferation of breast cancer." (PMID 29179448, 2017). "SYF2 expression level was correlated with the histological grade and the prognosis of breast cancer." (PMID 29179448, 2017). "With these results, we demonstrated that SYF2 promoted the cell proliferation of breast cancer by serum starvation-release experiment." (PMID 29179448, 2017). "However, in other studies, SYF2 expression was upregulated in cancer tissues compared to that in normal tissues as the tumor grade increased in ovarian and breast cancers." (PMID 36294892, 2022). "It was furthermore shown that the exon 5 inclusion variant of ECT2 increased tumor growth of doxorubicin-resistant breast cancer cells and resistance to chemotherapy in vivo, suggesting that this AS event contributed to the resistance induced by SYF2 or ZRANB2 overexpression." (PMID 34065983, 2021). "High mRNA levels of ZRANB2 and SYF2 did not associate with bad prognosis in our cohort of breast cancer patients treated with chemotherapy (data not shown)." (PMID 31943118, 2020). "We postulated that SYF2 might have a significant impact on the development of breast cancer in a cell cycle-dependent pathway." (PMID 29179448, 2017). "Based on these experimental data, it is now possible to strongly assume that SYF2 might potentially be a novel tumor marker or even molecular target for the treatment of breast cancer." (PMID 29179448, 2017). "In the present study, we investigated the role of SYF2 in human breast cancer (BC) progression." (PMID 29179448, 2017). "However, the role of SYF2 in breast cancer development remains obscure." (PMID 29179448, 2017). "First, accumulation of SYF2 was found in breast tumor lumen, triple-negative breast cancer, and HER2-positive breast cancer." (PMID 36118875, 2022).
breast carcinoma (continued). "The expression patterns of SYF2 and CPN2 in other breast cancer studies and in studies of other tumor types were both opposite to the findings of this study." (PMID 36294892, 2022). "In the detection of disease expression profiles, SYF2 was significantly expressed in breast tumor lumen, triple-negative breast cancer, and HER2-positive breast cancer." (PMID 36118875, 2022). "In all three cases, exon inclusion was higher in MCF7-DoxoR versus MCF-7 cells, and was decreased by both ZRANB2 and SYF2 depletion in MCF7-DoxoR cells and in two additional breast cancer cell lines." (PMID 31943118, 2020). "Altogether, our data identify AS programs controlled by ZRANB2 and SYF2 and converging on ECT2, that participate to breast cancer cell resistance to doxorubicin." (PMID 31943118, 2020). "Thus, SYF2 might have a similar impact on breast cancer cells." (PMID 29179448, 2017). "In the present study, we identify two convergent AS regulatory pathways (ZRANB2 and SYF2 splicing factors converging on ECT2 splicing) that control resistance to Doxo in breast cancer, specifically in ER+ERBB2- tumors (the main subtype of breast cancer)." (PMID 31943118, 2020). "The NTR protein SYF2 was, together with the zinc finger RNA-binding splicing factor ZRANB2, identified as a putative therapeutic target in a small siRNA screen silencing 19 spliceosome proteins that were found overexpressed in doxorubicin-resistant breast cancer cells." (PMID 34065983, 2021).
epithelial ovarian cancer (2 papers, 2017 to 2022). "Recent evidence implicates that SYF2 participates in progress of diverse tumor entities, such as liver cancer, ovarian cancer, lung cancer, and esophageal cancer." (PMID 29179448, 2017).
triple-negative breast carcinoma (2 papers, 2020 to 2022). An invasive breast carcinoma which is negative for expression of estrogen receptor (ER), progesterone receptor (PR), and human epidermal growth factor receptor 2 (HER2). "Consistently, we found that depletion of the ECT2-Ex5+ isoform (as well as depletion of ZRANB2 or SYF2) did not affect Doxo survival in two triple-negative breast cancer cell lines." (PMID 31943118, 2020).
osteoarthritis (1 paper, 2026). A noninflammatory degenerative joint disease occurring chiefly in older persons, characterized by degeneration of the articular cartilage, hypertrophy of bone at the margins and changes in the synovial membrane. "Spliceosome-associated factor 2 (SYF2) has been reported in tumors and neurological diseases, but not in studies of osteoarthritis." (PMID 42094020, 2026).
prostate adenocarcinoma (1 paper, 2025). "It was determined that 21 proteins (DHX9, EIF5, HPRT1, INPP5B, MCM6, PPP6C, SYF2, etc.)whose expression was increased in PC3‐R cells based on label‐free nLC‐MS/MS analysis were consistent with both TCGA prostate adenocarcinoma N0 and N1 nodal metastasis status and correlation data." (PMID 39799471, 2025).
cancer (6 papers, 2016 to 2025). A tumor composed of atypical neoplastic, often pleomorphic cells that invade other tissues. "The regulation of the cell cycle by SYF2 is also associated with the occurrence of many cancers." (PMID 36118875, 2022). "In addition, the analysis of expression patterns showed that SYF2 is associated with the occurrence of cancer in breast, lung, spleen, and reproductive organs, as well as other diseases." (PMID 36118875, 2022). "There is a positive correlation between SYF2 expression and proliferation of cancer, with SYF2 a potential novel tumor marker and an oncogene." (PMID 36118875, 2022). "This suggests that SYF2 may be involved in the development of disease, and may be a molecular target for the treatment of cancer." (PMID 36118875, 2022). "SYF2 might potentially be the molecular target for the treatment of cancer, i.e., knocking down SYF2 would lead to cell cycle G1/S phase arrest, and hence to inhibition of cancer cell proliferation." (PMID 36118875, 2022). "SYF2 interacts with Cyclin D-type binding-protein 1 (GICP), is involved in cell cycle regulation and pre-mRNA splicing, and plays an important role in cancer progression." (PMID 36118875, 2022). "It would be interesting to determine, whether the S-phase accumulation phenotype and the AS regulatory pathways (involving ZRANB2, SYF2 and ECT2-Ex5) that we identified, may be related to the cancer stem cell phenotype of Doxo-resistant cells." (PMID 31943118, 2020). "In the pan-cancer cohort, comprising 505 tumors the promoter regions with the most significant FM bias comprise a shortlist of interesting candidate drivers, such as those of TERT, SYF2, ARGHEF18, and POLR2D." (PMID 27311963, 2016).
tumor (4 papers, 2008 to 2022). "This study aims to reveal the relationship between SYF2 genotypes and biological disease processes from the perspective of bioinformatics, and to provide some basic theories for subsequent research into SYF2 as a novel tumor marker." (PMID 36118875, 2022). "The SYF2 expression level had a significant correlation with the tumor grade and Ki-67 expression." (PMID 29179448, 2017). "Furthermore, the expression of SYF2 was positively correlated with Ki-67 and tumor grade." (PMID 29179448, 2017).
SYF2 also shares sentences with these, for which no sentence is quoted: breast tumor (2 papers); esophageal cancer (2); ovarian cancer (2); animal diseases (1); cardiac disease (1); colon cancer (1); colorectal adenoma (1); esophageal squamous cell carcinoma (1); gastric cancer (1); glioma (1); heart failure (1); liver cancer (1); lung carcinoma (1); melanoma (1); neurological diseases (1); non-small cell lung carcinoma (1).